ZNF367 (zinc finger protein 367)
Description:
Transcriptional activator. Isoform 1 may be involved in transcriptional activation of erythroid genes.
Synonyms: ZFF29; FLJ33970; AFF29
Tractability: PROTAC: ubiquitination databases record sites on it.
Gene: Protein-coding gene on chromosome 9 (96,385,941 to 96,418,370, reverse strand). Ensembl gene ENSG00000165244.
Subcellular location: Nucleus
Subcellular location (Human Protein Atlas): Nucleoplasm
Gene Ontology:
Molecular function: DNA-binding transcription factor activity; DNA-binding transcription factor activity, RNA polymerase II-specific; RNA polymerase II cis-regulatory region sequence-specific DNA binding
Biological process: regulation of transcription by RNA polymerase II
Cellular component: nucleoplasm; nucleus
Genetic constraint (gnomAD): Loss-of-function variants: 9 observed, 27.86 expected, observed/expected ratio (o/e) 0.32, 90% interval 0.19 to 0.56. The upper end of that interval is the gene's LOEUF score, 0.56, which puts it in group 2 of 6, group 1 being the genes least tolerant of losing a copy. Missense variants: 295 observed, 380.91 expected, observed/expected ratio (o/e) 0.77, 90% interval 0.7 to 0.85. Synonymous variants: 174 observed, 154.25 expected, observed/expected ratio (o/e) 1.13, 90% interval 1 to 1.28.
Homologues: Orthologues: chimpanzee ZNF367 (99% identical), macaque ZNF367 (99% identical), pig ZNF367 (94% identical), dog ZNF367 (93% identical), rat Zfp367 (90% identical), mouse Zfp367 (89% identical), guinea pig ZNF367 (69% identical), zebrafish znf367 (65% identical), tropical clawed frog znf367 (64% identical), Drosophila melanogaster klu (15% identical), Caenorhabditis elegans klu-2 (13% identical), Drosophila melanogaster CG4318 (12% identical). Paralogues in human: ZBTB7A (22% identical), ZBTB5 (18% identical), ZBTB43 (13% identical), ZNF740 (10% identical).
Diseases named in the same sentence as ZNF367 in open-access papers:
ZNF367 is named in the same sentence as 24 diseases in open-access papers, as found by Europe PMC text mining. Sharing a sentence is not in itself a finding about the gene and the disease. The quoted sentences say what the papers report.
breast carcinoma (9 papers, 2017 to 2024). "The miR-21–5p carried by hucMSCs-Exo binds to the 3’-untranslated region (3’-UTR) of ZNF367 to inhibit the progression of breast cancer." (PMID 38994350, 2024). "ZNF367 inhibited tumor growth, proliferation, migration, and invasion of breast cancer, promoting tumor invasion and metastasis." (PMID 38994350, 2024). "In metastatic breast cancer, up-regulated expression of zinc finger protein 367 (ZNF367) inhibited Hippo signaling pathway, giving rise to anoikis resistance and increased CTCs in circulation." (PMID 36313283, 2022). "Overall, ZNF367 positively regulated KIF15 through transcriptionally activating KIF15 in breast cancer." (PMID 32549756, 2020). "In short, ZNF367-activated KIF15 accelerated the progression of breast cancer by regulating cell cycle progress." (PMID 32549756, 2020). "On the whole, this study uncovered that ZNF367-activated KIF15 accelerated the progression of breast cancer and exerted the vital functions on cell cycle." (PMID 32549756, 2020). "Furthermore, verteporfin reduced the expression of YAP in the ZNF367-overexpressing breast cancer MDA-MB-231 and 4T1 cells, and significantly reduced lung metastases in mouse models." (PMID 34771636, 2021). "And rescue experiments indicated that overexpressed KIF15 could counteract the inhibition effect of silencing ZNF367 on the progression of breast cancer." (PMID 32549756, 2020). "Taken together, silencing of ZNF367 restrained cell growth and migration in breast cancer." (PMID 32549756, 2020). "Moreover, ZNF367 could induce the transcriptional activation of kinesin family member 15, leading to elevated cell viability and invasion ability in breast cancer cells." (PMID 35768832, 2022). "In addition, functional experiments demonstrated that silenced ZNF367 could repress cell growth of breast cancer." (PMID 32549756, 2020). "In addition, silenced ZNF367 could also repress the growth of breast cancer cells." (PMID 32549756, 2020). "Taken together, ZNF367 transcriptionally activated KIF15 and accelerated the progression of breast cancer." (PMID 32549756, 2020). "It was indicated that ZNF367 and KIF15 could regulate cell cycle in breast cancer so as to accelerate the progression of breast cancer." (PMID 32549756, 2020). "In short, these results demonstrated that ZNF367 and KIF15 could regulate cell cycle in breast cancer." (PMID 32549756, 2020). "Furthermore, we identified several unreported tissue-specific TFs that may contribute to breast cancer, including ATOH8, DMRT2, TBX15 and ZNF367." (PMID 28036274, 2017). "In addition, this study found the following tissue specific TFs that were not reported in breast cancer: ATOH8, DMRT2, TBX15 and ZNF367." (PMID 28036274, 2017).
adrenocortical carcinoma (4 papers, 2014 to 2020). "In Human SW13 adrenocortical carcinoma cell line, znf367 is overexpressed and in this cell line Znf367 downregulation caused an increase of cellular proliferation, invasion and migration." (PMID 30087422, 2018). "We show that ZNF367 is overexpressed in adrenocortical carcinoma, malignant pheochromocytoma/paraganglioma and thyroid cancer as compared to normal tissue and benign tumors." (PMID 25047265, 2014). "There was stronger ZNF367 staining in the nucleus than in the cytoplasm in each cancer sample (adrenocortical cancer, papillary thyroid cancer and malignant pheochromocytoma/paraganglioma)." (PMID 25047265, 2014). "ZNF367 was expressed in adrenocortical carcinoma (SW13, BD140A), papillary thyroid cancer (TPC-1), and HEK293 cell lines." (PMID 25047265, 2014). "To confirm the elevated expression of ZNF367 in adrenocortical carcinoma in a larger sample set, we analyzed expression profiling data from publicly available datasets deposited in gene expression omnibus." (PMID 25047265, 2014). "We found that ZNF367 was overexpressed in a variety of endocrine cancers (adrenocortical carcinoma, papillary thyroid cancer, malignant pheochromocytoma/paraganglioma) compared to benign and or normal tissue samples." (PMID 25047265, 2014). "In two independent genome-wide gene expression data sets, ZNF367 was overexpressed in adrenocortical carcinoma compared to adrenal cortical adenoma and normal tissue samples (p<0.001)." (PMID 25047265, 2014). "ZNF367 is overexpressed in adrenocortical carcinoma, papillary thyroid cancer, and malignant pheochromocytoma/paraganglioma, compared to benign and normal tissue samples for each tumor type (p<0.05)." (PMID 25047265, 2014). "In this study, we determined the mechanism of gene expression regulation and function of ZNF367 in a variety of endocrine cancers (papillary thyroid cancer, adrenocortical carcinoma, pheochromocytoma/paraganglioma)." (PMID 25047265, 2014). "In addition, compared with normal tissues, ZNF367 expression level is higher in malignant paraganglioma, adrenocortical carcinoma and thyroid cancer." (PMID 33028966, 2020). "However, contrary to these three TFs, ZNF367 was over-expressed in adrenocortical carcinoma, malignant pheochromocytoma, paraganglioma and thyroid cancer." (PMID 28036274, 2017).
adrenal cortical adenoma (2 papers, 2014 to 2020). "Zinc finger protein 367 (ZNF367) is overexpressed in ACC compared to benign adrenal adenomas." (PMID 32079166, 2020).
endocrine cancers (2 papers, 2014 to 2020). "Here, we report that ZNF367 is overexpressed in a variety of endocrine cancers and that it inhibits in vitro and in vivo growth, cellular invasion, migration, and adhesion." (PMID 25047265, 2014). "Because ZNF367 is overexpressed in endocrine cancer, we investigated its effect on cellular proliferation, invasion, and migration, events that are necessary for cancer progression." (PMID 25047265, 2014).
adrenocortical tumor (1 paper, 2014). "Moreover, ITGA3 mRNA expression was inversely correlated with ZNF367 mRNA expression in human adrenocortical tumor samples (r = - 0.37, p = 0.015)." (PMID 25047265, 2014).
colon cancer (1 paper, 2020). "A later study in a familial form of colon cancer also was able to zoom in to a region around 9q22.2-31.2, in which aside the gene of HABP4 only three other genes are found, which seem to be less likely candidates for oncoproteins or tumor suppressors (ZNF367, GABBR2 and GALNT12)." (PMID 33245729, 2020).
colorectal cancer (1 paper, 2023). A primary or metastatic malignant neoplasm that affects the colon or rectum. "For example, ZNF212 and ZNF367 can regulate the apoptosis of ovarian tumour cells and the proliferation of colorectal cancer cells, respectively." (PMID 36803542, 2023).
lung adenocarcinoma (1 paper, 2025). A carcinoma that arises from the lung and is characterized by the presence of malignant glandular epithelial cells. "The results revealed that MYBL2, CENPA, FOXM1, E2F1, ZNF367, and HMGA1 are the most relevant upstream transcription factors in lung adenocarcinoma." (PMID 40885709, 2025).
lung squamous cell carcinoma (1 paper, 2023). "In addition, SLC46A2, ZNF367, AC107214.1 and NCBP1 genes were identified as survival-related genes of patients with lung squamous cell carcinoma." (PMID 37185598, 2023).
tumor (10 papers, 2014 to 2026). "Lastly, we demonstrate that dysregulated ZNF367 expression was associated with the loss of miR-195 expression in tumor samples and that this microRNA directly targets ZNF367 and regulates cellular invasion, providing an understanding of the mechanism for dysregulated ZNF367 expression." (PMID 25047265, 2014). "Dissemination of circulating tumor cells is crucial for distant metastasis, and YAP1 increases the number of circulating tumor cells following activation by the chromatin remodeling protein ZNF367." (PMID 33178014, 2020). "Following, we discovered that ZNF367 level was higher in 36 tumor tissues than that in paratumor tissues (left)." (PMID 32549756, 2020). "Moreover, in silico analysis of human tumor sample genome-wide gene expression analysis demonstrated an inverse relationship between ZNF367 and ITAG3 expression." (PMID 25047265, 2014). "CCT5, LCOR, and ZNF367 were evidently overexpressed in tumor tissues compared with adjacent tissues (all P < 0.001), while FOS was significantly downregulated in tumor tissues compared with non-tumor tissues of HCC patients (P < 0.001)." (PMID 34522182, 2021). "Additionally, PTTG1 may correlate with the BLCA tumor microenvironment and exert transcriptional activity by targeting CHEK2, OCIAD2, UBE2L3, and ZNF367 in BLCA tissue." (PMID 35768832, 2022). "Mainly, survival analyses showed that the same expression of SLC46A2, ZNF367, AC107214.1 and NCBP1 genes in the primary and LNM lesions can provides more potent prognostic information when no analyses of the primary tumor have been done." (PMID 37185598, 2023).
cancer (6 papers, 2011 to 2024). A tumor composed of atypical neoplastic, often pleomorphic cells that invade other tissues. "Some of the genes, correlated to znf367 in our correlation analysis are both implicated in CNS development as well as in cancer initiation and/or progression." (PMID 30087422, 2018). "ZNF367 expression is directly regulated by miR-195, and the loss of miR-195 is associated with increased ZNF367 in human cancer samples." (PMID 25047265, 2014). "Similarly, OCIAD2, UBE2L3, and ZNF367 also displayed intimate association with cancer development." (PMID 35768832, 2022). "The involvement of znf367 in the control of cell cycle is supported by functional studies that demonstrated its implication in regulating different aspects of cancer progression." (PMID 30087422, 2018). "Nonetheless, using both knockdown and overexpression strategies, we found that ZNF367 inhibited cancer growth and invasion, which suggests that the elevated levels in cancer samples are counter-regulatory and inhibit cancer progression." (PMID 25047265, 2014). "We propose that the loss of miR-195 expression results in the increased expression of ZNF367 and a miR-195-ZNF367 axis that is important in inhibiting cancer progression." (PMID 25047265, 2014). "To understand the mechanism by which ZNF367 expression is dysregulated in cancer, we postulated that microRNAs may be responsible for ZNF367 overexpression." (PMID 25047265, 2014). "This is the first study to characterize the expression and function of ZNF367 in cancer." (PMID 25047265, 2014). "Our findings taken together suggest that ZNF367 regulates cancer progression." (PMID 25047265, 2014). "In summary, ZNF367 inhibits cancer progression by modulating cellular growth and invasion." (PMID 25047265, 2014). "Zinc finger protein 367 (ZNF367) belongs to the zinc finger protein family and is overexpressed in various types of cancer." (PMID 38994350, 2024). "However, the role of ZNF367 in cancer has not been investigated." (PMID 25047265, 2014).
benign tumor (2 papers, 2014 to 2021). "ZNF367 was overexpressed in ACCs compared to normal tissue and benign tumor and reduced cellular proliferation, invasion, migration and adhesion to extracellular proteins both in vitro and in vivo." (PMID 34829730, 2021).
ZNF367 also shares sentences with these, for which no sentence is quoted: thyroid cancer (3 papers); malignant pheochromocytoma (2); papillary thyroid cancer (2); paraganglioma (2); cervical cancer (1); digestive system carcinoma (1); glioblastoma (1); glioma (1); liver disease (1); nervous system diseases (1); osteosarcoma (1); ovarian tumour (1).